CDK14 (cyclin dependent kinase 14)
Description:
Serine/threonine-protein kinase involved in the control of the eukaryotic cell cycle, whose activity is controlled by an associated cyclin. Acts as a cell-cycle regulator of Wnt signaling pathway during G2/M phase by mediating the phosphorylation of LRP6 at 'Ser-1490', leading to the activation of the Wnt signaling pathway. Acts as a regulator of cell cycle progression and cell proliferation via its interaction with CCDN3. Phosphorylates RB1 in vitro, however the relevance of such result remains to be confirmed in vivo. May also play a role in meiosis, neuron differentiation and may indirectly act as a negative regulator of insulin-responsive glucose transport.
Synonyms: PFTK1; PFTAIRE1
Tractability: Small molecule: a drug acting on it is in phase 2 or 3 trials; a high-quality ligand is known; it belongs to a druggable protein family. Antibody: its Gene Ontology location is reachable by antibodies, with high confidence; UniProt places it where antibodies can reach, with medium confidence. PROTAC: it is named in the literature on targeted protein degradation; ubiquitination databases record sites on it; its protein half-life has been measured; a small molecule that binds it is known.
Target class: Enzyme; CMGC protein kinase CDK family; CMGC protein kinase PFTAIRE; CMGC protein kinase group; Kinase; Protein Kinase
Chemical probes: JA397 (high quality)
Gene: Protein-coding gene on chromosome 7 (90,466,424 to 91,210,590, forward strand). Ensembl gene ENSG00000058091.
Subcellular location: Cell membrane; Cytoplasm; Nucleus
Subcellular location (Human Protein Atlas): Nucleoplasm; Cytosol
Gene Ontology:
Molecular function: cyclin binding; cyclin-dependent protein serine/threonine kinase activity; protein binding; ATP binding; protein kinase activity; protein serine kinase activity
Biological process: G2/M transition of mitotic cell cycle; regulation of canonical Wnt signaling pathway; regulation of cell cycle phase transition
Cellular component: cyclin-dependent protein kinase holoenzyme complex; cytoplasmic cyclin-dependent protein kinase holoenzyme complex; cytosol; nucleoplasm; plasma membrane; cytoplasm; nucleus
Genetic constraint (gnomAD): Loss-of-function variants: 17 observed, 28.54 expected, observed/expected ratio (o/e) 0.6, 90% interval 0.41 to 0.89. The upper end of that interval is the gene's LOEUF score, 0.89, which puts it in group 3 of 6, group 1 being the genes least tolerant of losing a copy. Missense variants: 263 observed, 335.22 expected, observed/expected ratio (o/e) 0.78, 90% interval 0.71 to 0.87. Synonymous variants: 113 observed, 127.38 expected, observed/expected ratio (o/e) 0.89, 90% interval 0.76 to 1.04.
Homologues: Orthologues: macaque CDK14 (99% identical), chimpanzee CDK14 (99% identical), dog CDK14 (99% identical), pig CDK14 (99% identical), mouse Cdk14 (99% identical), rabbit CDK14 (98% identical), tropical clawed frog cdk14 (93% identical), rat Cdk14 (91% identical), guinea pig CDK14 (73% identical), zebrafish cdk14 (62% identical). Paralogues in human: CDK15 (52% identical), CDK18 (46% identical), CDK16 (45% identical), CDK17 (45% identical), CDK11B (35% identical), CDK11A (35% identical), CDK5 (34% identical), CDK3 (33% identical), CDK12 (33% identical), CDK2 (32% identical), CDK1 (32% identical), CDK13 (31% identical), and 14 more.
Diseases named in the same sentence as CDK14 in open-access papers:
CDK14 is named in the same sentence as 42 diseases in open-access papers, as found by Europe PMC text mining. Sharing a sentence is not in itself a finding about the gene and the disease. The quoted sentences say what the papers report.
glioma (11 papers, 2019 to 2023). A benign or malignant brain and spinal cord tumor that arises from glial cells (astrocytes, oligodendrocytes, ependymal cells). "CDK14 reportedly participates in the proliferation and invasion of many tumor cells, including those of breast cancer, glioma, hepatocellular carcinoma, and ovarian cancer." (PMID 33635431, 2021). "Besides, CDK14 expression was higher in glioma than normal and took part in glioma progression regulated by miR-613." (PMID 32605563, 2020). "Furthermore, CDK14 functioned as an oncogene in glioma and served as a target gene of miR-613." (PMID 32605563, 2020). "Among the circRNAs whose expression had been validated in glioma, circCDK14 (hsa_circ_0001721), derived from exons 3 of CDK14 (cyclin-dependent kinase 14), is interested by us." (PMID 35002529, 2022). "However, the function of circRNAs derived from CDK14 in glioma remains unknown." (PMID 35002529, 2022). "The endogenous linear CDK14 mRNA levels, however, did not alter with circCDK14 overexpression or silencing of in glioma cells." (PMID 35002529, 2022).
hepatocellular carcinoma (11 papers, 2011 to 2025). A malignant tumor that arises from hepatocytes. "Comparative data about the role of CDK14 in cancer is sparse, but authors relate that the over-expression of CDK14 promotes Wnt signaling, predicts chemotherapeutic resistance, and increases hepatocellular carcinoma motility." (PMID 25162504, 2014). "In invasive hepatocellular carcinoma (HCC) and pancreatic cancer, CDK14 overexpression promotes invasiveness and migration and activating mutations of CDK14 have been identified in HPV + HCC patients." (PMID 39800748, 2025). "In hepatocellular carcinoma (HCC), miR-877-5p targets cyclin-dependent kinase 14 to suppress the proliferation, migration, and invasion of HCC cells." (PMID 34232111, 2021).
breast carcinoma (9 papers, 2015 to 2023). "Reports on breast cancer demonstrated that an allele-specific copy-number imbalance in CDK14 was related to poor prognosis." (PMID 29875348, 2018). "DYRK2 expression is inversely related to TERT and cyclin-dependent kinase 14 (CDK14) expression in the breast cancer tissues of invasive ductal carcinoma." (PMID 37886981, 2023). "Consistent with the results previously reported in breast cancer cell lines, miR-455 also inhibited the CDK14 expression in OS cell lines." (PMID 29022909, 2017). "CDK14 has been shown to interact with other cyclins as well, such as cyclin B to activate the Wnt pathway in breast cancer, cyclin D3 to regulate cell cycle progression and proliferation in mammalian cells, and the CDK7/cyclin H complex to regulate proliferation and migration in esophageal cancer." (PMID 34571979, 2021).
osteosarcoma (9 papers, 2017 to 2024). A usually aggressive malignant bone-forming mesenchymal neoplasm, predominantly affecting adolescents and young adults. "CDK14 was discovered to be associated with overall survival and prognosis in osteosarcoma patients." (PMID 36740668, 2023). "It was reported that a high expression of CDK14 was associated with poor prognosis in osteosarcoma, and miR-216a was found to target CDK14, resulting in the inhibition of cell proliferation, invasion, and metastasis of osteosarcoma." (PMID 29875348, 2018). "The miR-216a/CDK14 axis promoted Wnt pathway in osteosarcoma cells via modulating LRP6 phosphorylation and Wnt downstream genes." (PMID 36740668, 2023). "For instance, miR-216a targets CDK14 to suppress the proliferation and invasion of osteosarcoma cells." (PMID 32711584, 2020). "thus promoting tumorigenesis through LINC00858/miR-139/CDK14 axis in osteosarcoma, as a ceRNA for miR-422a to facilitate cell proliferation in NSCLC." (PMID 32419983, 2020). "MiR-216a down regulated CDH2 while up regulated CDH1 via CDK14 targeting in osteosarcoma." (PMID 36740668, 2023). "MiR-216a inhibited osteosarcoma cell growth and invasion by down regulating CDK14." (PMID 36740668, 2023). "Besides, OIP5-AS1 accelerated CDK14 abundance to contribute to osteosarcoma tumorigenesis via functioning as a sponge of miR-223." (PMID 32410883, 2020). "MiR-216a/CDK14 axis was also essential in the phosphorylation of PI3K and Akt in osteosarcoma cells." (PMID 36740668, 2023). "For example, in osteosarcoma, OIP5-AS1 has been reported to serve as a ceRNA of miR-223 to regulate CDK14 expression and mediate osteosarcoma cell proliferation and apoptosis." (PMID 35602889, 2022).
ovarian carcinoma (9 papers, 2017 to 2026). A malignant neoplasm originating from the surface ovarian epithelium. "For instance, miR‐539‐3p acts as a tumor suppressor by inhibiting CDK14 in colon cancer cells, while it promotes ovarian cancer by targeting SPARCL1." (PMID 41584930, 2026). "Recent studies have identified potential mechanisms for the development of paclitaxel resistance involving TGFB pathways in ovarian cancer cell lines via and cyclin dependent kinase 14 (CDK14) mediated mechanisms." (PMID 41465326, 2025). "Another lncRNA, MSC-AS1, promoted cancer progression in gastric, colorectal, hepatocellular, melanoma, and ovarian cancer, and was shown to up-regulate CDK14 expression by acting as a molecular sponge for miR-29b-3p." (PMID 38279317, 2024). "However, according to the reported studies, CDK14 is a target of miR-128-3p and miR-128-3p downregulation increases CDK14 expression and thus promotes cell proliferation, migration, invasion and inhibits apoptosis in ovarian cancer." (PMID 34493213, 2021). "However, the specific function and regulatory mechanism of CDK14 on paclitaxel (PTX) resistance in ovarian cancer (OC) remain unclear." (PMID 37670966, 2023).
pancreatic cancer (7 papers, 2017 to 2025). "CDK14 silencing strongly suppressed pancreatic cancer cell proliferation and invasion, as well as EMT progression via inhibition of the PI3K/Akt signaling pathway." (PMID 35002529, 2022). "In pancreatic cancers, CDK14 has been revealed as a hub gene in the interaction network including the Wnt/β-catenin pathway and phosphoinositide 3-kinase/Akt signaling pathway, and its increased expression is associated with poorer overall patient survival." (PMID 33635431, 2021). "In addition, knockdown of CDK14 inhibits the expression of p-PI3K and p-Akt in pancreatic cancer cells." (PMID 29022909, 2017).
prostate carcinoma (7 papers, 2018 to 2025). A carcinoma that arises from epithelial cells of the prostate gland. "The abnormal increase in CDK14 levels in prostate cancer is linked to METTL1-mediated modification of its mRNA expression in an m7G manner, resulting in enhanced CDK14 mRNA stability." (PMID 40809690, 2025). "In prostate cancer, it was mentioned that N7-methylguanosine modification after Cdk14 transcription increases mRNA stability, which in turn contributes to the pathologic growth of prostate cancer." (PMID 39827158, 2025). "Prior investigations have suggested that the classical m7G writer METTL1 may undergo transcriptional upregulation by the transcription factor (TF) SP1, thereby stabilizes CDK14 mRNA and contributes to the progression of prostate cancers." (PMID 38385078, 2024). "Finally, the role of CDK14, the most atypical cell cycle-dependent kinase, in prostate cancer and its mechanism of action still needs to be further explored." (PMID 37599359, 2023). "It has been observed that E2F transcription factor 5 (E2F5) and/or PFTAIRE Protein Kinase 1 (PFTK1, also known as CDK14) are upregulated in various types of human cancers, including prostate cancer." (PMID 30185212, 2018). "Notably, in prostate cancer, METTL1 stabilizes CDK14 mRNA by catalyzing internal m7G modification, resulting in the upregulation of CDK14, which in turn promotes tumor cell proliferation and invasion." (PMID 38385078, 2024).
non-small cell lung carcinoma (5 papers, 2017 to 2025). A group of at least three distinct histological types of lung cancer, including non-small cell squamous cell carcinoma, adenocarcinoma, and large cell carcinoma. "Small nucleolar RNA host gene 15 (SNHG15) has been shown to provide a potential therapeutic effect through the regulation of CDK14 protein by sponging miR-486 in non-small-cell lung cancer (NSCLC) patients." (PMID 34079751, 2021). "Similarly, in non-small cell lung cancer, two studies have demonstrated that SNHG15 knockdown suppresses tumorigenesis by inhibiting the expression of EMT, MMP2, and MMP9 and regulating the miR-486/CDK14 axis." (PMID 33243205, 2020).
colon cancer (4 papers, 2014 to 2026). "Whereas expression levels of CCNY, CCNYL1, and CDK16 were broadly comparable across all cell types, the average level of CDK14 was more than an order of magnitude lower in colon cancer cells compared to any other tissue included in this analysis." (PMID 34571979, 2021). "For instance, the serine/threonine kinase PFTK1 (or CDK14), a member of the CDC2-related protein kinase family, positively modulates the protein levels of SMO, PTCH1 and GLI1, thus controlling cell proliferation, invasion and EMT in colon cancer cells." (PMID 30934935, 2019). "One propagated tumor line, CBP1, from a model ES cell line overexpressing CDK14 in addition to β-Catenin was tested to assess whether a propagatable colon tumor lacking KRAS activation and CDK6 amplification would respond to either of the targeted agents or their combination." (PMID 25162504, 2014).
gastric cancer (4 papers, 2015 to 2023). A primary or metastatic malignant neoplasm involving the stomach. "CDK14, also known as Pftk1, is also overexpressed in gastric cancer, and is involved in promoting metastasis and invasion of tumors." (PMID 36769170, 2023).
glioblastoma (4 papers, 2020 to 2025). The most malignant astrocytic tumor (WHO grade IV). "Other genes hypomethylated and overexpressed in PTCL - RAB13, MPZL1, CDK14- were implicated in tumor progression of several different tumors including B-cell lymphomas, and glioblastomas, lung and ovarian." (PMID 38464090, 2024).
lung carcinoma (4 papers, 2017 to 2025). "Given its stronger upregulation and reported association with lung cancer metastasis, CDK14 was selected for further analysis." (PMID 41016985, 2025). "Silencing SNHG15 reduced the expression of CDK14 in A549 and H460 lung cancer cells, with CDK14 being the gene involved in regulating cell cycle progression." (PMID 37056344, 2023).
triple-negative breast carcinoma (4 papers, 2023 to 2025). An invasive breast carcinoma which is negative for expression of estrogen receptor (ER), progesterone receptor (PR), and human epidermal growth factor receptor 2 (HER2). "In 2019, FMF-04-159-2 (FMF) was found to covalently bind to CDK14, which can reduce the activity of breast stem cells and inhibit the progression of triple-negative breast cancer." (PMID 39827158, 2025). "Cdk14 has been reported to be enriched in malignant tumors, including triple-negative breast cancer." (PMID 39827158, 2025). "Given CDK14 is expressed in the mammary basal layer and is elevated in triple-negative breast cancer, it may contribute to tumor aggressiveness." (PMID 40791616, 2025). "To confirm these developmental defects in Cdk14 knockout mice, we made use of a CDK14 antagonist, namely FMF-04-159-2 (hereinafter abbreviated as FMF), which covalently binds to the CDK14 protein with a selective inhibitory effect on the progression of triple-negative breast cancer." (PMID 39827158, 2025). "In triple-negative breast cancer, the CDK14/CCNY complex phosphorylates the membrane receptor LRP6 and regulates the activity of breast cancer stem cells through the Wnt/β-catenin signaling pathway, ultimately promoting the progression and metastasis of triple-negative breast cancer." (PMID 37599359, 2023).
liver cancer (3 papers, 2015 to 2024). An epithelial or non-epithelial malignant neoplasm that arises from the liver. "Furthermore, in liver cancer tissues and cells, miR-877-5p is downregulated and it inhibits the proliferation, migration, and invasion of liver cancer cells by targeting CDK14." (PMID 38309290, 2024).
lymphoma (3 papers, 2021 to 2024). A malignant (clonal) proliferation of B- lymphocytes or T- lymphocytes which involves the lymph nodes, bone marrow and/or extranodal sites. "Several genes from this group, such as UHRF1, MPZL1, CDK14, RACGAP1, RAB13, and others have oncogenic functions in various solid tumors, leukemias, and lymphomas either predicting poor prognosis, involved in tumor migration, metastasis, or maintenance." (PMID 38464090, 2024). "Moreover, 47 cell proliferation-associated genes were found downregulated in Ri-1 cells under hypoxia, including cyclin CCNB1, and cyclin-dependent kinases CDK14, CDK15, and CDK16, which have significant involvement in the lymphoma pathogenesis." (PMID 34440794, 2021).
melanoma (3 papers, 2022 to 2024). A malignant, usually aggressive tumor composed of atypical, neoplastic melanocytes. "However, our findings suggest that high expression of CDK14 is associated with better prognosis and anti-PD-1 therapy response in melanoma patients, implying a unique mechanism of CDK14 in melanoma." (PMID 35479936, 2022). "As an important member of CAFs-related genes, CDK14 can predict the effect of anti-PD-1 treatment in melanoma patients." (PMID 39072320, 2024). "Using WGCNA combined with supervised machine learning algorithms, we identified a novel CAFs-related panel, including six genes (CDK14, SYNPO2, TCF4, GJA1, CPXM1, TFPI), which can distinguish the response of melanoma patients under anti-PD-1 immunotherapy." (PMID 35479936, 2022).
colorectal cancer (2 papers, 2021 to 2024). A primary or metastatic malignant neoplasm that affects the colon or rectum. "FMF-04-159-2 was recently designed to provide an improved pharmacological tool for the inhibition of CDK14 as treatment for colorectal cancer." (PMID 38575601, 2024). "We observed that, in contrast to other cells included in this assay, CDK14 was not detectable in the colorectal cancer cell lines at our disposal." (PMID 34571979, 2021).
esophageal squamous cell carcinoma (2 papers, 2012 to 2023). Esophageal squamous cell carcinoma (ESCC) is a type of esophageal carcinoma (EC) that can affect any part of the esophagus, but is usually located in the upper or middle third. "Although it has been reported that the high expression of CDK14 correlates with chemoresistance in esophageal squamous cell carcinoma 17, the relationship between CDK14 and PTX resistance in OC has not been disclosed yet." (PMID 37670966, 2023).
breast tumor (1 paper, 2020). "The blockade of TIM-3 in breast tumor explants downregulated genes related to cancer pathways, including those associated with tumor cell proliferation/migration/invasion (WNT5A, LIF, XDH2, SNAI, CDH2, ADAMST12, PLAU, and CDK14)." (PMID 32616706, 2020).
cerebral malaria (1 paper, 2018). A sequestration of Plasmodium falciparum in the brain, which can cause coma and/or seizures. "The five identified proteins (ANK1, CD14, CDK14, ELANE, MPP1) were found to be elevated in the febrile convulsion group compared to cerebral malaria." (PMID 30442134, 2018).
cervical cancer (1 paper, 2023). A primary or metastatic malignant neoplasm involving the cervix. "Furthermore, it triggers the progression of ovarian and cervical cancers by sequestering miR-128-3p and promoting the expression of cyclin-dependent kinase 14 (CDK14) and RNA-binding protein Musashi-2 (MSI2)." (PMID 37998733, 2023).
cutaneous melanoma (1 paper, 2019). A primary melanoma arising from atypical melanocytes in the skin. "Our study also proposes genes ESM1, NFATC3, C7orf4, CDK14, ZNF827, and ZSWIM7 as novel putative markers for cutaneous melanoma metastasis." (PMID 31673075, 2019).
endometriosis (1 paper, 2023). The growth of functional endometrial tissue in anatomic sites outside the uterine body. "Since LINC01279 expression in endometriosis tissues was markedly increased and connected with cyclin-dependent kinase 14 (CDK14) expression, LINC01279 may control endometriosis’ cell cycle." (PMID 37455911, 2023).
malaria (1 paper, 2022). Malaria is a serious and sometimes fatal disease caused by a parasite that commonly infects a certain type of mosquito which feeds on humans. "Interestingly, Cdk14 is regulated by the anticonvulsant drug valproic acid and is up-regulated in malaria patients who experience febrile convulsions." (PMID 35456420, 2022).